CTSB (cathepsin B)
Diseases named in the same sentence as CTSB in open-access papers (continued):
Sharing a sentence is not in itself a finding about the gene and the disease.
Hepatitis (3 papers, 2018 to 2025). Inflammation of the liver. "The arsenic-induced pyroptosis in NASH involved autophagy, CTSB, and the NLRP3 inflammasome cascade, and that taurine alleviated As2O3-induced liver inflammation by inhibiting the autophagic-CTSB-NLRP3 inflammasomal pathway rather than decreasing lipid accumulation." (PMID 36324154, 2022). "This last observation could explain why in the α-GalCer model, where TNF is involved in α-GalCer-induced upregulation of FasL on NKT cells, but hepatocyte damage depends mainly on FasL, CTSB inhibition did not protect against α-GalCer mediated hepatitis." (PMID 29541077, 2018).
hookworm infection (3 papers, 2012 to 2019). "We demonstrate here that the highly expressed, substantially intestine-enriched cathepsin B cysteine protease, AceyCP1, is a promising protective antigen candidate for vaccination against A. ceylanicum hookworm infection in Syrian hamsters." (PMID 31009474, 2019).
invasive breast carcinoma (3 papers, 2016 to 2022). A carcinoma that infiltrates the breast parenchyma. "Loss of CSTA expression is associated with progression of ductal breast cancer in situ to invasive breast cancer, presumptively via increased cathepsin B activity which raises the possibility that cathepsin B may be a relevant therapeutic target in aGCT." (PMID 26893359, 2016).
ischemic stroke (3 papers, 2017 to 2024). A stroke disorder caused by obstruction of blood flow to the brain, due to thrombotic (local blood clot formation) or embolic (due to a blood clot or other material traveling from another site) event. "A recent study also demonstrated that EE promoted autophagy by increasing the expression of beclin-1 and enhancing the lysosomal activities of lysosomal-associated membrane protein 1, cathepsin B, and cathepsin D, which eventually boosted neurological function recovery following ischemic stroke." (PMID 34646128, 2021).
kidney cancer (3 papers, 2022 to 2024). Primary or metastatic malignant neoplasm involving the kidney. "CTSB and FDFT1 are associated with ferroptosis in pancreatic and kidney cancer, respectively." (PMID 36902448, 2023).
leishmaniasis (3 papers, 2016 to 2023). Infectious disease that is transmitted through the bite of hematophagous female phlebotomine sand flies. "Cathepsin B inhibitors were already shown to have favorable effect in leishmaniasis, but the mechanisms behind these effects remain unclear." (PMID 27182703, 2016). "Cathepsin B has already been proposed as a therapeutic target for inflammatory diseases, and for leishmaniasis, and our work brings forth new evidence on the effects that cathepsin B inhibition might have at the T cell level, and sets the stage for future investigation." (PMID 27182703, 2016).
lung adenocarcinoma (3 papers, 2016 to 2021). A carcinoma that arises from the lung and is characterized by the presence of malignant glandular epithelial cells. "The CTSB gene was closely related to the occurrence and development of lung adenocarcinoma." (PMID 33238959, 2020). "In the first comparison, proteins which most contributed to discriminate between 58 malignant (of which half were lung adenocarcinomas and half mesotheliomas) and their corresponding paired TB effusions were MMP-9, cathepsin-B, C-reactive protein, angiostatin, and chondroitin sulfate." (PMID 26962828, 2016).
lysosomal storage disease (3 papers, 2015 to 2025). A metabolic disorder caused by mutations in proteins critical for lysosomal function, including lysosomal enzymes, lysosomal integral membrane proteins, and proteins involved in the post-translational modification and trafficking of lysosomal proteins. "Axonal swellings containing autophagosome-like structures are observed in mouse models of lysosomal storage diseases such as neuronopathic GD mice, Niemann-pick type C1 mice, Cathepsin D-deficient mice, and Cathepsin B/L double-deficient mice." (PMID 25835295, 2015). "Cathepsin B, a lysosomal hydrolase, plays a significant role in lysosomal storage disorders that share similar pathological features with Parkinson’s disease." (PMID 39420987, 2024).
medulloblastoma (3 papers, 2016 to 2024). A malignant, invasive embryonal neoplasm arising from the cerebellum. "In addition, miR-204 downregulates M6PR, IGF2R genes involved in the lysosomal segregation of cathepsin B and cathepsin D lysosomal enzymes in medulloblastoma cells." (PMID 38611021, 2024). "Therefore, effect of miR-204 expression on the levels of lysosomal enzymes Cathepsin B and Cathepsin D in medulloblastoma cells was studied by western blotting." (PMID 30944042, 2019). "Furthermore, reduction in the levels of lysosomal enzymes Cathepsin B and Cathepsin D upon miR-204 expression in medulloblastoma cells suggests impairment of the lysosomal degradation pathway." (PMID 30944042, 2019).
memory impairment (3 papers, 2020 to 2025). "This implies that the abnormal expression of CTSB in AD plays a crucial role in memory impairment, and this role may be associated with interactions between neurons and glial cells." (PMID 40919134, 2025). "Ultimately, the reconstitution of the miR‐96‐5p/CTSB signaling pathway effectively rescued astrocyte reactivity and memory impairment in AD." (PMID 40919134, 2025). "The neuronal inflammatory mediator CTSB reactivates adjacent astrocytes and contributes to memory impairment during AD progression." (PMID 40919134, 2025). "Briefly, hippocampal infusion of miR‐96‐5p agomirs or intraperitoneal injection of CA‐074, a CTSB inhibitor, reduced astrocyte reactivity in the hippocampus and effectively ameliorated memory impairment in 3×Tg mice." (PMID 40919134, 2025). "Our findings suggest that the neuron‐derived inflammatory mediator CTSB reactivates adjacent astrocytes and mediates memory impairment in early AD." (PMID 40919134, 2025). "Furthermore, some studies suggest that CTSB drives memory impairment in AD by activating neuroinflammatory responses in microglial cells." (PMID 40919134, 2025). "In this study, we investigated the effect of GF diets in a mouse model of AD prior to the development of amyloid plaques to show how this treatment paradigm would alter the accumulation of Aβ peptide and related pathologic changes (i.e., inflammation, cathepsin B, and memory impairment)." (PMID 33396967, 2020).
metastatic melanoma (3 papers, 2013 to 2022). A melanoma that has spread from its primary site to another anatomic site. "It is reported that inhibition of cathepsin B by either a specific chemical inhibitor, CA-074, or specific anti-cathepsin B antibodies significantly prevented the in vitro invasiveness of metastatic melanoma cell lines." (PMID 35563798, 2022).
papillary thyroid carcinoma (3 papers, 2011 to 2023). "Association of CTSB rs12898 G/A polymorphism with clinical characteristics of papillary thyroid carcinoma." (PMID 36510340, 2023). "CTSB upregulation in papillary thyroid cancer correlates with positive lymph node metastasis and cancer cell migration via p38-mediated EMT." (PMID 35459137, 2022). "In pathological conditions, however, such as papillary thyroid carcinoma, cathepsin B has been localized to the basement membrane." (PMID 21835049, 2011).
preeclampsia (3 papers, 2017 to 2022). Preeclampsia is a hypertensive disorder of pregnancy that is characterized by new-onset hypertension with proteinuria presenting after 20 weeks of gestation, and depending on mild or severe forms may initially present with severe headache, visual disturbances, and hyperreflexia. "Cathepsin B expression in human trophoblast is positively correlated with the trophoblast invasiveness and preeclampsia." (PMID 34462873, 2022). "The present study shows that women with late-onset preeclampsia have significantly higher serum cathepsin B and D concentrations than controls, and cathepsin B concentrations are even higher in the subgroup of preeclampsia that has severe features." (PMID 31360581, 2019). "The aim of the study was to assess serum cathepsin B, D, and L concentrations in women with late-onset preeclampsia." (PMID 31360581, 2019). "Women with late-onset preeclampsia have significantly higher serum cathepsin B and D concentrations than controls." (PMID 31360581, 2019). "Cathepsin B concentrations were significantly higher in women with preeclampsia with severe features compared with those with preeclampsia alone." (PMID 31360581, 2019). "The aim of the study was to assess serum cathepsin B, D, and L concentrations in women with late-onset preeclampsia and to determine the impact of cathepsins with regard to the presence of severe features." (PMID 31360581, 2019). "This is the first study to demonstrate the impact of cathepsin B, D, and L on late-onset preeclampsia." (PMID 31360581, 2019). "Cathepsin B concentrations were found to be positively correlated with uric acid concentrations (r=0.343, p<0.01) in women with preeclampsia." (PMID 31360581, 2019). "Cathepsin B concentrations were significantly higher in women with preeclampsia with severe features (n=26) compared with those with preeclampsia alone (6.89±3.51 ng/mL vs. 3.31±3.02 ng/mL, respectively; p<0.001)." (PMID 31360581, 2019). "Moreover, cathepsin B concentrations were found to be positively correlated with uric acid concentrations in women with preeclampsia." (PMID 31360581, 2019). "The ROC curve of cathepsin B in predicting severe preeclampsia was analyzed." (PMID 31360581, 2019). "Additionally, to our knowledge this is the first study to evaluate serum cathepsin B, D, and L concentrations in late-onset preeclampsia." (PMID 31360581, 2019). "In summary, the study suggests that cathepsin B and D may be promising biomarkers in women with late-onset preeclampsia." (PMID 31360581, 2019). "PRECIS: Cathepsin B and D may be promising biomarkers in women with late-onset preeclampsia." (PMID 31360581, 2019). "Cathepsin B and D may be promising biomarkers in women with late-onset preeclampsia." (PMID 31360581, 2019).
prostate adenocarcinoma (3 papers, 2018 to 2023). "However, prostate adenocarcinoma (PRAD) had a lower CTSB expression." (PMID 35155389, 2022).
Pseudomonas infection (3 papers, 2016 to 2025). Infections with bacteria of the genus pseudomonas. "Conversely, the downregulation of alkaline phosphatase and cathepsin B may explain the significant reduction in offspring size, endogenous growth rate, and perinatal growth rate after Pseudomonas infection." (PMID 40266768, 2025). "For instance, NE has been shown to regulate the expression of cysteine proteases (CTSB) and MMPs (MMP-2) in a murine Pseudomonas infection model and in human macrophages." (PMID 34065111, 2021).
rectum adenocarcinoma (3 papers, 2019 to 2024). An adenocarcinoma arising from the rectum. "However, upon further differential gene expression comparative analysis, it was noted that although all genes except OPRM1 and ADRA1A showed expression in colon and rectal adenocarcinoma, their levels of expression were not as high as CTSB and CPNE1, which demonstrated the maximum expression." (PMID 38544823, 2024).
renal carcinoma (3 papers, 2019 to 2020). A carcinoma arising from the epithelium of the renal parenchyma or the renal pelvis. "We used established RCC models to test the significance of CTSB in the progression of renal cancer." (PMID 30796200, 2019).
sarcopenia (3 papers, 2025). Progressive decline in muscle mass due to aging which results in decreased functional capacity of muscles. "As a preclinical target for hair loss and bone cancer, the potential of CTSB as a drug target for sarcopenia warrants further validation." (PMID 39949133, 2025). "Our MR analysis observed that CTSB was negatively associated with the whole body FFM, suggesting that it is a potential risk factor for sarcopenia." (PMID 39949133, 2025). "Among them, the significant associations of CTSB (negative association) and ASGR1 (positive association) with sarcopenia‐related traits were observed to have consistent directional associations in both MR‐based studies and observational studies." (PMID 39949133, 2025).
triple-negative breast carcinoma (3 papers, 2011 to 2024). An invasive breast carcinoma which is negative for expression of estrogen receptor (ER), progesterone receptor (PR), and human epidermal growth factor receptor 2 (HER2). "Green-light-triggered release of the cathepsin B (CTSB) inhibitor 18 led to a shift in the type of cell death in MDA-MB-231 triple-negative breast cancer cells from apoptosis to necrosis." (PMID 38675140, 2024). "A role for cathepsin B has previously been reported in several triple-negative breast cancer cell lines that are not IBC (e.g., BT20, BT549, MCF-10AneoT, and MDA-MB-231), and inhibition of active cathepsin B in these cells reduced their invasion in vitro." (PMID 22093547, 2011).
type 1 diabetes (3 papers, 2021 to 2023). "In the heart of a type 1 diabetes mouse model, cathepsin B is released from lysosomes, which activates NLRP3, triggering pyroptosis." (PMID 36742461, 2023). "Similarly, CTSB can induce NLRP3-mediated pyroptosis in the heart of type 1 diabetic mouse." (PMID 36742461, 2023).
viral myocarditis (3 papers, 2018 to 2026). Myocarditis that is caused by an infection with a viral agent. "It has been reported that CTSB aggravates CVB3-induced viral myocarditis, probably through activating the inflammasome and promoting pyroptosis." (PMID 30534113, 2018).
abdominal aortic aneurysm (2 papers, 2022). Enlargement and ballooning of the vessel that supplies arterial blood to the abdomen, pelvis and legs. "Cysteine proteases have also been linked to the occurrence of abdominal aortic aneurysms, with aortic wall samples showing significantly higher expression of cathepsin B, H, L and S, supporting the postulation that cathepsins are involved in aneurysm expansion." (PMID 41541591, 2022).
active tuberculosis (2 papers, 2021 to 2025). "However, in Mycobacterium tuberculosis-infected rabbits, increased CTSB gene expression was observed in the lungs, and increased protein levels were observed in plasma from patients with active tuberculosis." (PMID 40422803, 2025). "In this context, we have focus on one SNV in the AIM2 inflammasome in tuberculosis together with two other SNVs, one in CARD8 and one in CTSB, that are related to NLRP3 pathway." (PMID 33868225, 2021).
appendicitis (2 papers, 2022 to 2023). Acute inflammation of the vermiform appendix. "The results of this study prioritize HLX and CTSB as potential causal genes for appendicitis and suggest a shared genetic mechanism between appendicitis and CRP concentrations." (PMID 35693796, 2022). "Our results prioritize HLX and CTSB as potential causal genes for appendicitis and suggest a shared genetic mechanism between appendicitis and CRP concentrations." (PMID 35693796, 2022). "The locus at 8p23.1 contains multiple genes, including cathepsin B (CTSB), which is overexpressed in appendix tissue from appendicitis patients." (PMID 35693796, 2022). "The inflammasome pathway, which includes CTSB, was significantly upregulated in plasma from appendicitis patients compared to patients with sexually transmitted infection-induced endometritis (adjusted p = 0.0017)." (PMID 35693796, 2022). "The expression of CTSB was significantly higher in the appendix of appendicitis patients compared to individuals who were undergoing intra-abdominal surgery for a non-inflammatory condition (p = 0.0004)." (PMID 35693796, 2022). "Importantly, CRP is known as a potential biomarker for acute appendicitis and its severity in children, yet a study revealed that HLX and CTSB genes are possible etiologies for appendicitis and propose a shared genetic mechanism between appendicitis and CRP levels." (PMID 37873776, 2023). "Therefore, it is tempting to speculate that CTSB and PITX2 may affect similar molecular pathways to cause appendicitis." (PMID 35693796, 2022).
bipolar disorder (2 papers, 2012 to 2020). A disorder of the brain that causes unusual shifts in mood, energy, activity levels and the ability to carry out day-to-day tasks. "In addition, low levels of cathepsin B staining were seen in the hippocampus of an individual with a history of neuropsychological impairment due to schizophrenia and bipolar disorder." (PMID 22693552, 2012).
Brain atrophy (2 papers, 2023 to 2024). Partial or complete wasting (loss) of brain tissue that was once present. "However, CTSB also possesses neuroprotective and anti-amyloidogenic properties, and mice studies have revealed neuronal loss and brain atrophy in double-KO mice lacking both CTSB and CTSL." (PMID 39286235, 2024). "Interestingly, neuronal loss and brain atrophy has been observed in mice lacking CTSB, suggesting a role for cathepsin B in neuronal maintenance." (PMID 37681909, 2023).
chronic myelogenous leukemia (2 papers, 2022 to 2023). "In chronic myelogenous leukemia CD34+ cells, imatinib induced CTSB activation, and overexpression of CTSB sensitized these cells to imatinib killing." (PMID 37576397, 2023).
chronic pancreatitis (2 papers, 2014 to 2025). A chronic inflammatory process causing damage and fibrosis of the pancreatic parenchyma. "Notably, Cst3−/− mice did not develop spontaneous forms of acute or chronic pancreatitis, even in the presence of higher CTSB activity within the secretory compartment." (PMID 39962054, 2025).
cutaneous melanoma (2 papers, 2020 to 2022). A primary melanoma arising from atypical melanocytes in the skin. "Primary cutaneous melanoma cells incubated with cathepsin B for 24 h, the cell apoptosis rate was increased in a dose-dependent manner." (PMID 33335896, 2020). "This demonstrates that CEP can inhibit the growth of primary cutaneous melanoma by inhibiting autophagy and cathepsin B." (PMID 33335896, 2020). "But CEP has been poorly studied in cutaneous melanoma, and in our study, it not only downregulates cathepsin B levels but also possesses novel antitumor mechanisms and inhibits primary cutaneous melanoma activity and metastasis by either topical application or intra-tumoral injection in mice." (PMID 33335896, 2020). "Although progress has been made in the study of cathepsin B as a target for cancer gene therapy in combination with conventional chemotherapeutic agents, the role of cathepsin B in the proliferation of human primary cutaneous melanoma and its possible biological mechanism remain unclear to date." (PMID 33335896, 2020).
cystinosis (2 papers, 2022 to 2025). Cystinosis is a metabolic disease characterized by an accumulation of cystine inside the lysosomes, causing damage in different organs and tissues, particularly in the kidneys and eyes. "Conversely, CTSB-dependent albumin catabolism promotes glutathione synthesis by exporting cystine from lysosomes via the transporter cystinosis fuels, thereby inhibiting lethal lipid peroxidation." (PMID 40895546, 2025).
demyelinating disease (2 papers, 2019 to 2020). A broad group of disorders that affect the myelin sheaths that cover the neurons. "Data indicate cathepsin B as a key molecule mediating neurodegeneration, opening research pathways for therapeutic targeting of LSDs and other demyelinating diseases." (PMID 30530526, 2019).